CHEK2 (checkpoint kinase 2)
Diseases named in the same sentence as CHEK2 in open-access papers (continued):
Sharing a sentence is not in itself a finding about the gene and the disease.
cancer (continued). "In this study, we aimed to characterize germline CHEK2 variants from a group of individuals who applied to cancer genetic clinics in the Marmara Region of Türkiye." (PMID 39594831, 2024). "Due to its important role in vital cellular processes, genetic mutations in CHEK2 that influence CHK2 protein function affect cancer risk." (PMID 39594831, 2024). "The association between germline mutations in the CHEK2 gene and the development of various types of cancer, including PTC, has been reported in numerous case-control studies." (PMID 38398207, 2024). "We analyzed electronic health record (EHR) in two population-based cohorts (UK Biobank (UKBB) and Geisinger MyCode) to estimate the prevalence, age-dependent penetrance, cancer risk and survival of CHEK2 pathogenic heterozygotes compared to controls." (PMID 39371170, 2024). "Missense pathogenic or likely pathogenic (P/LP) variants in CHEK2 seem to confer a similar cancer risk to the loss-of-function variant 1100delC." (PMID 39594831, 2024). "Here, we report 9 out of 24 patients with non-contributory family history, harboring germline heterozygous deleterious mutation in well-known cancer predisposing genes (CHEK2, RAD51C, BRCA2, FANCA, RET, FH, and BAP1)." (PMID 38700789, 2024). "The analysis of function revealed that harmful missense variants in CHEK2 were linked to a higher risk of cancer." (PMID 37965453, 2023). "Cell cycle regulator CHEK2 controls the homologous recombinant DNA repair process, suppresses tumors, and genetic changes in it render cancers more susceptible to more advanced targeted therapies." (PMID 37732318, 2023). "For cancer-free AJ women the probability of having a pathogenic mutation in CHEK2 is 1.4%–1.7% and the chance for a mutation in BRCA1 or BRCA2 is less than 2.5%." (PMID 36845387, 2023). "Two families shared variants in genes associated with DNA damage response and involved in cancer development (CHEK2 and RAD54L)." (PMID 36765901, 2023). "The results of this study highlight the importance of targeted development of selective inhibitors specific to CHEK2 as potential treatments preventing PMF loss during genotoxic cancer therapy." (PMID 37862420, 2023). "Larger multicenter studies will improve our understanding of the incidence, phenotype, and molecular biology of CHEK2 germline variants in pediatric cancers." (PMID 36980535, 2023). "In this study, we present our single-institution experience regarding six children and adolescents with CHEK2 germline alterations and cancer or cancer-predisposing conditions, including their clinical presentations and outcomes." (PMID 36980535, 2023). "Presently, the contribution of the germline CHEK2 variant to predisposition to the cancers described in this case series is unclear." (PMID 36980535, 2023). "The variants in PMS2 and CHEK2 were classified as pathogenic in ClinVar, with reported cancer associations." (PMID 38136396, 2023). "Mutations in the CHEK2 gene, which encodes Chk2, has been shown to increase the risk of developing a few different cancers." (PMID 39524544, 2023). "In conclusion, we functionally categorized a majority of germline CHEK2 missense variants commonly occurring in patients with cancer and controls in various populations worldwide." (PMID 37449874, 2023). "Broader studies will improve our understanding of the true incidence of these variants and of the biologic contribution of CHEK2 germline and somatic alterations in pediatric cancers." (PMID 36980535, 2023). "Genetic variants in the CHEK2 gene have been associated with an increased risk of breast, prostate, and other cancers." (PMID 37347260, 2023). "A multiorgan cancer susceptibility gene, CHEK2, is one of the most frequently identified genes harboring germline alterations in patients with various cancers, including in children, adolescents, and young adults." (PMID 36980535, 2023).
cancer (continued). "Checkpoint kinase 2 (CHEK2) germline loss-of-function variants have been reported in pediatric cancer patients, but clinical phenotypes and outcomes are poorly described." (PMID 36980535, 2023). "The checkpoint kinase 2 (Chk2) regulates cell-cycle progression, and Chk2 dysregulation or Chk2 mutations can lead to the development of various cancers, which makes Chk2 an important research topic." (PMID 39524544, 2023). "CHEK2 is a multi-organ cancer predisposition gene playing an important role in cell cycle regulation and DNA damage repair, two processes involved in cancer development and response to treatment." (PMID 36717774, 2023). "Ataxia Telangiectasia Mutated (ATM) protein activates CHEK2 to prevent the buildup of mutations and reduce the risk of cancer when DNA is damaged." (PMID 37732318, 2023). "More research is needed to determine the magnitude of the cancer risk related to a specific gene alteration and to advise patients who have a variant in the CHEK2 or ATM genes." (PMID 37239898, 2023). "In the current study, we found phenotypic heterogeneity among patients carrying the same CHEK2 mutation, which has potentially important clinical implications when evaluating the risk of developing cancer." (PMID 38476463, 2023). "We present our single-institution experience with six children with CHEK2 germline alterations and cancer or cancer-predisposing conditions, including their clinical presentations and outcomes." (PMID 36980535, 2023). "First, the CHEK2 functional analysis, based on a combination of KAP1/CHK2 assays with a high-content microscopy controlling the intracellular targeting of analyzed variant in human non-cancer cells, scored concordantly for 340 variants." (PMID 37449874, 2023). "While CHEK2 loss-of-function mutations are rare in human cancer cell lines, we identified a cell line, Colo678, that harbored biallelic loss-of-function mutations in CHEK2." (PMID 35110534, 2022). "Two of these variants were positively associated in our analysis of any 2+ primary cancers: rs555607708 (CHEK2; OR [95% CI] = 1.57 [1.09, 2.25], p = 0.015) and rs146381257 (ZNF106; OR [95% CI] = 5.38 [1.07, 27.18], p = 0.042)." (PMID 36199081, 2022). "Two of these 20 patients were also found to have pathogenic variants in a second cancer predisposition gene, CHEK2 in one patient, and MSH6 in the other (patient ID: 6 and 235 respectively)." (PMID 35710434, 2022). "Abnormalities in cell proliferation and apoptotic evasion due to CHEK2 gene mutations have been observed in various cancers." (PMID 35626065, 2022). "Among the 15 canonical genes associated with CH, our cancer patients had mutations in CHEK2, DNMT3A, ASXL1, PPM1D, and TET2 only." (PMID 35428225, 2022). "In our database, CHEK2 was found to have pathogenic variants with an overall prevalence of 2.2% and was the gene most likely associated with a family history of cancer and among NHW patients." (PMID 35040284, 2022). "Because of numerous recognized CHEK2 sequence variants with different phenotypic effects, and due to its expression in a variety of tissues, the full scope of cancers associated with inactivating mutations of CHEK2 has yet to be determined." (PMID 35267514, 2022). "The association between CHEK2 and other cancers, including the male breast, kidney, gastric, prostate, lung, ovarian, and thyroid cancers, was also reported." (PMID 35281821, 2022). "The third most frequently altered gene in our cohort was CHEK2, which has been previously linked to increased risk of developing most the common gender-specific cancers: breast and prostate." (PMID 36290365, 2022). "The Copenhagen retrospective cohort study reported the incidence of different types of cancer in a cohort of 670 carriers of a heterozygous CHEK2 c.1100delC mutation in comparison to a cohort of 86.305 non-carriers." (PMID 35101071, 2022).
cancer (continued). "In a study performed on mice and reported by Bahassi, it was found that subjects with CHEK2*1100delC SNP were predisposed to cancer with a strong gender bias." (PMID 35885460, 2022). "CHEK2 was the second most commonly altered gene with a total of 28 (7.4%) variants, and 124 (32.8%) genetic variants were found in other 35 cancer-associated genes with variable penetrance." (PMID 36290365, 2022). "CHEK2 GPVs, particularly c.1100delC and p.I157T, are also associated with increased risks of other types of cancer, such as colorectal, prostate, kidney, and thyroid cancer." (PMID 35806485, 2022). "Two known pathogenic moderate cancer risk variants were also found in participant A; in the genes CHEK2 and HOXB13." (PMID 34711244, 2021). "Relative to BRCA1 and BRCA2, less is known of the role of BRIP1 and CHEK2 cancer predisposing genes in conferring risk of BC and OC in FCs." (PMID 34298626, 2021). "The polymorphisms RAD51/G135C, ATM/P1054R, and CHEK2/T470C were selected because they were associated with many cancers, such as prostate, breast, head and neck cancer, and leukemias." (PMID 33778923, 2021). "Molecular profiling of the patient’s tumor also identified a novel HER2 mutation affecting the protein tyrosine kinase domain and a CHEK2 mutation previously identified as a cancer susceptibility gene in the Finnish population." (PMID 34604070, 2021). "In the cancers where defects occur to corrupt DNA repair and facilitate tumorigenesis, a CHEK2 strong association has been observed." (PMID 34630562, 2021). "A recent paper identified the DNA double-strand break signaling kinase ataxia-telangiectasia mutated (ATM) and its downstream target checkpoint kinase 2 (Chk2) as regulators of Aurora B recruitment to the midbody center in human cancer cells." (PMID 34943860, 2021). "In contrast, Cybulski and colleagues analyzed two founder truncations, c.1100delC and c.444+1G>A, and the p.I157T missense variant in a large group of Polish patients and characterized CHEK2 as a multi-organ cancer susceptibility gene." (PMID 33322746, 2020). "A significantly younger cancer onset in CHEK2 mutation carriers has been reported less consistently." (PMID 33322746, 2020). "Alterations in the CHEK2 gene have been consistently associated with an increased risk for breast cancer development and, more recently, with other types of cancer, such as colorectal and kidney cancers." (PMID 32708810, 2020). "Case reports of homozygous carriers, which included other CHEK2 mutations, have been published episodically, and they indicate an increased risk of the development of variable primary cancers with an early age at onset." (PMID 33322746, 2020). "The missense CHEK2 I157T allele was found in 4,8% of controls, and it was more common in cancer cases than in controls—the association was significant at the p ≤ 0.01 level." (PMID 32570972, 2020). "So far, the c.1100delC and p.I157T CHEK2 variants are the most comprehensively studied, being associated in large case–control studies with increased risk for different types of cancer, such as testicular germ cell tumours, breast and colorectal cancers." (PMID 33158149, 2020). "Although several germline variants in the CHEK2 gene have been associated with increased cancer risk, the knowledge regarding the full mutational spectra and specific variant-associated risk, particularity in PrCa, is still limited." (PMID 33158149, 2020). "While all cancer predisposition genes are now equal from the perspective of germline testing, the clinical utility of several genes (including CHEK2) varies in a broad interval delimited by their penetrance and population-specific prevalence." (PMID 33322746, 2020). "Despite known and possible cancer associations for CHEK2 PV carriers, phenotypic differences between monoallelic and biallelic carriers are not yet understood." (PMID 31993860, 2020). "It is difficult to refer to the association between FATWO and CHEK2-related cancers, because of its rarity." (PMID 32570972, 2020).
cancer (continued). "An increased risk for breast and other cancers has been documented in individuals who carry a single pathogenic CHEK2 variant." (PMID 31349801, 2019). "Many studies have reported that genetic variants in ATR/CHEK1 and ATM/CHEK2 are associated with cancer risk." (PMID 29928473, 2018). "It has been well-established in multiple studies that germline CHEK2 mutations are associated with an increased risk for breast, colon and other cancers." (PMID 29659587, 2018). "In one male participant we identified a pathogenic CHEK2 variant, which leads to a dominantly inherited moderate lifetime risk for cancers including breast and colorectal." (PMID 30487145, 2018). "In this retrospective study, we analyzed the presence of CHEK2 mutation and its relationship with cancers in family history of patients with ccRCC." (PMID 29682443, 2018). "The National Comprehensive Cancer Network's (NCCN) guidelines regarding cancer risk and management for the CHEK2 gene are based on frameshift mutations." (PMID 30152102, 2018). "The authors suggest further studies regarding the gene-gene interaction between CHEK2 gene and other tumor suppressor genes to demonstrate the cancer risk in Iranian women." (PMID 28680382, 2017). "Direct follow up studies, particularly on ROF mutations in the tumor suppressors TGFBR1 and CHEK2 will be necessary before these mutations can be confirmed as bona fide cancer drivers." (PMID 28743916, 2017). "CHEK2 is a multiorgan cancer susceptibility gene that encodes a multifunctional serine/threonine protein kinase." (PMID 27484185, 2016). "The aim of the present study was to determine the CHEK2 R95* mutation incidence and potential influence on cancer risk across the general population." (PMID 27708748, 2016). "We have shown that CHEK2 is down-regulated in most cancer-associated fibroblasts (CAFs) as compared to their corresponding tumor counterpart fibroblasts (TCFs) at both the mRNA and protein levels." (PMID 27484185, 2016). "The severity of the symptoms is likely to be variable for CHEK2 mutations, and accumulation of more cases will clarify CHEK2’s role in cancer development." (PMID 27900359, 2016). "Taken together, these, and other data clearly indicates CHEK2 to be a multi-cancer susceptibility gene, with truncating mutation being of particular importance for some cancer types." (PMID 27708748, 2016). "While germline CHEK2 mutations have been linked to a moderately elevated cancer risk, to date, a limited number of such mutations have been identified." (PMID 27708748, 2016). "Multiple studies on low penetrance cancer susceptibility alleles showed that alterations in the CHEK2 gene increase the risk of different malignancies." (PMID 25798211, 2015). "We focused on identifying mutations in BRCA1, BRCA2 and PALB2 and the CHEK2 c.1100delC mutation, as the risks for the development of breast and associated cancers with these genes have been determined by analysing large study populations." (PMID 26577449, 2015). "Some missense substitutions in CHEK2 also alter cancer risk, as exemplified by the Ashkenazi CHEK2 missense substitution p.S428F and the Slavic substitution p.I157T." (PMID 21244692, 2011). "In certain populations, one or a few mutations do indeed capture the majority of CHEK2 variants associated with cancer risk." (PMID 22114986, 2011). "Uncertainty remains as to the best estimate of cancer risk for gene carriers, and the factors which influence the penetrance of the CHEK2 gene." (PMID 19401704, 2009). "In the simplest manifestation of a two-gene model, it would be necessary for a carrier of a deleterious CHEK2 mutation also to carry a specific allele of a second gene to develop cancer." (PMID 19401704, 2009). "We wished to establish the relationship between family history, mutation type and cancer risk in families with a CHEK2 mutation." (PMID 19401704, 2009). "CHEK2 mutations predispose men and women to a range of cancer types, including breast, prostate and colon." (PMID 19401704, 2009).
cancer (continued). "It is important to have accurate knowledge of the range of cancers associated with various CHEK2 mutations, and of the lifetime risks of cancer associated with each." (PMID 19401704, 2009). "These analyses suggest that the risk of cancer in a carrier of a CHEK2 mutation is dependent on the family history of cancer." (PMID 19401704, 2009). "The emerging picture suggests that some functionally significant variants in CHEK2 are able to predispose cells from a wide distribution of organs to an elevated risk of cancer." (PMID 18706089, 2008). "CHEK2 is a multiorgan cancer susceptibility gene encoding a cell cycle checkpoint kinase acting in the DNA-damage response signalling pathway." (PMID 18831734, 2008). "Rare somatic mutations in CHEK2 have also been identified in a number of cancer types, including lung and ovarian cancers and osteosarcomas." (PMID 14612911, 2003). "Testing for CHEK2 mutations may be recommended for individuals with a family history of cancer or other risk factors." (PMID 39996890, 2025). "Individuals with mutated CHEK2 have an increased risk of developing cancer at a young age and may benefit from increased cancer surveillance and preventative measures." (PMID 39996890, 2025). "Shortly after, CHEK2 emerged as a multiorgan cancer susceptibility gene." (PMID 40492861, 2025). "Also, PD-L2 levels were significantly higher in PR patients positive for this CHEK2 variant (p = 0.048), underscoring the need to explore its potential therapeutic role for this cancer." (PMID 40146757, 2025). "In addition, an exome sequencing study in BC patients demonstrated that USP39 regulates cancer-associated tumor suppressors, including CHEK2, and has a tumor-inducing effect." (PMID 40990019, 2025). "The CHEK2 variant is associated with an increased risk of cancer." (PMID 41459527, 2025). "Future studies focused on CHEK2 LR variants will aid in better understanding whether these variants are genetic modifiers associated with cancer risk." (PMID 39745704, 2025). "However, the BC risk for a woman carrier of the CHEK2 mutation is not only dependent on the presence of the mutation itself but also on the familial history of cancers." (PMID 40508121, 2025). "From a hereditary standpoint, pathogenic CHEK2 variants—well established in other cancers like breast—appear to confer at most a low-to-moderate increase in RCC risk: associations (including with I157T and c.1100delC) have been reported but are inconsistent and show limited penetrance." (PMID 41440218, 2025). "This variation raises the possibility that other genetic modifiers, such as variations in DNA repair genes like XRCC1 and XPD, could increase the risk of cancer in people with CHEK2." (PMID 40507526, 2025). "USP39 regulates cancer-associated tumor suppressors including CHEK2 and induces tumorigenesis." (PMID 40990019, 2025). "Furthermore, following the initial discovery and characterization of CHEK2 variants, these mutations have also been found in association with several cancers." (PMID 40492861, 2025). "Additionally, we analyzed known risk variants for cancer susceptibility in Central and Eastern Europe, CHEK2 p.Ile157Thr (population prevalence in Estonia 8.6%), CHEK2 p.Thr367fs (0.6%), and CHEK2: c.319 + 2T>A (0.1%)." (PMID 40060932, 2025). "This suggests that PD-1/PD-L1 inhibitors may be more effective in CHEK2-deficient tumors, an observation which has been noted in both murine and pan-cancer studies." (PMID 40492861, 2025). "Prevalence of as well as cancer risk and survival in adults with CHEK2 germline variants." (PMID 41396600, 2025). "The patient also carried a germline CHEK2 variant of unknown significance, raising concerns for cancer predisposition." (PMID 40630716, 2025). "Thus, we also included CHEK2 c.470C>T in further analyses considering its association with cancer risk, despite having conflicting classifications of pathogenicity." (PMID 40506802, 2025).